LGI1 (leucine rich glioma inactivated 1)
Diseases named in the same sentence as LGI1 in open-access papers (continued):
Sharing a sentence is not in itself a finding about the gene and the disease.
encephalitis (continued). "The patients with LGI1-antibody encephalitis showed asymmetric FDG uptake that was frequently located in the hippocampus (11/13, 84.6%) and the basal ganglia (7/13, 53.9%)." (PMID 30253786, 2018). "Patients with LGI1 antibody encephalitis are often normal in routine CSF tests; the positive rate of LGI1 antibody detection in CSF is lower than that in serum." (PMID 29980179, 2018). "Approximately 70% of patients with LGI1 antibody encephalitis have increased T2 and FLAIR MRI signals in the hippocampus or temporal lobe (unilaterally or bilaterally), and some can extend to the amygdala, insula or striatum." (PMID 29980179, 2018). "We therefore recommend using a combination of examinations to confidently and correctly diagnose LGI1 antibody encephalitis." (PMID 29980179, 2018). "More frequently, however, myoclonus has been reported in LGI1- and CASPR2-antibody-associated encephalitis, an important mimic of Creutzfeldt-Jakob disease (CJD)." (PMID 29053777, 2018). "Of the 13 patients with LGI1-antibody encephalitis, ten (76.9%) were male, and the median age was 64 years [IQR 61–72 years]." (PMID 30253786, 2018). "Eleven of the 13 LGI1-antibody encephalitis patients (84.6%) showed asymmetrical FDG high uptake in the hippocampus: nine (81.8%) on the left hippocampus and two (18.2%) on the right." (PMID 30253786, 2018). "Leucine-rich glioma-inactivated 1 (LGI1) antibody encephalitis is a rare autoimmune voltage-gated potassium channel complex (VGKC) antibody-associated limbic encephalitis." (PMID 29980179, 2018). "In our study, hyponatremia occurred in six patients, and three presented with refractory hyponatremia, highlighting the prevalence of hyponatremia in patients with LGI1 antibody encephalitis." (PMID 29980179, 2018). "Rituximab seems to be safe and effective even in a later course of the disease in patients with LGI1 antibody encephalitis." (PMID 30524441, 2018). "In comparison to NMDA-R-encephalitis, patients with LGI1-encephalitis usually seem to respond faster at the beginning of immunotherapy, although the long-term outcome tends to be less favorable." (PMID 30233481, 2018). "In agreement with previous studies, onset ages were typically around 60 years, and patients with LGI1 or CASPR2 antibodies most frequently had encephalitis or epilepsy." (PMID 29788256, 2018). "An abnormal MRI has been described in only 30% of patients with anti-NMDA-receptor-encephalitis (NMDARE) and with CASPR2-associated AE, an abnormal CSF in 20–40% of AE patients with CASPR2- and LGI1-antibodies." (PMID 29951031, 2018). "In view of similar clinical manifestations, the diagnosis of LGI1 antibody encephalitis need to be distinguished from viral encephalitis, Hashimoto’s encephalopathy, Creutzfeldt’s disease (CJD), and other forms of autoimmune encephalitis." (PMID 29980179, 2018). "Since antibody LGI1 encephalitis patients are characterized by acute or subacute onset of cognitive dysfunction, the disease has often been misdiagnosed as a mental illness in the past." (PMID 29980179, 2018). "Our study also showed that epilepsy and cognitive impairments were common and prominent clinical manifestations in patients with LGI1 antibody encephalitis." (PMID 29980179, 2018). "The high frequency of clinical and subclinical seizures suggests routine consideration of prolonged EEG monitoring to guide more aggressive seizure suppression in LGI1-antibody encephalitis." (PMID 28586706, 2017). "Our findings broaden the perspective on LGI1 encephalitis by not only looking at the target organ (the brain parenchyma) but also on the question of how the presumably pathogenic antibodies can enter it." (PMID 29093718, 2017). "The observed temporal, frontal and parietal electrical activities extend the pathology of LGI1-antibody encephalitis beyond the medial temporal lobes." (PMID 28586706, 2017).
encephalitis (continued). "Dyscognitive, autonomic, motor, gelastic and fearful seizures have previously been noted in LGI1-antibody encephalitis patients across studies with varying methodologies and inclusion criteria." (PMID 28586706, 2017). "Human leucine-rich glioma-inactivated protein 1 encephalitis (LGI1) is an autoimmune limbic encephalitis in which serum and cerebrospinal fluid contain antibodies targeting LGI1, a protein of the voltage gated potassium channel (VGKC) complex." (PMID 29093718, 2017). "This is also valid for the other forms of encephalitis, although patients with LGI1 antibodies have a lower frequency of CSF pleocytosis (41%) or elevated protein (47%) and rarely have intrathecal LGI1 antibody synthesis." (PMID 28261116, 2017). "In human LGI1 encephalitis, neuropathological investigations are difficult because very little material is available." (PMID 29093718, 2017). "Patients with LGI1-antibody encephalitis have a striking number of frequent, multifocal seizure localisations with multiple semiologies, in addition to faciobrachial dystonic seizures and numerous subclinical seizures." (PMID 28586706, 2017). "Leucine-rich glioma inactivated 1 (LGI1) antibody encephalitis can present with unusual behaviours including psychotic symptoms, usually together with neurological symptoms including seizures." (PMID 28363946, 2017). "Recently, we showed that a feline model of limbic encephalitis with LGI1 antibodies, called feline complex partial seizures with orofacial involvement (FEPSO), is highly comparable to human LGI1 encephalitis." (PMID 29093718, 2017). "Faciobrachial dystonic seizure (FBDS) is a novelcharacterized type of seizure, specific for anti-LGI1 encephalitis." (PMID 29213481, 2016). "With the exception of FBDS, which was a characteristic feature of anti-LGI1 encephalitis, seizure type and frequency were similar between antibody types." (PMID 26771547, 2016). "These two cases are illustrative presentations of anti-LGI1 encephalitis with FDBSand rapid cognitive decline." (PMID 29213481, 2016). "Faciobrachial dystonic seizures (FDBS) is a distinctive adult-onset, high-frequency,very brief and highly specific antiepileptic resistant seizure and almostpathognomonic for anti-leucine-rich-glioma inactivated 1 (LGI1)encephalitis." (PMID 29213481, 2016). "A Dutch nationwide study documented an annual incidence of anti-LGI1 encephalitis of0.83/million, which is similar to the incidences of CJD and Lambert Eaton myasthenicsyndrome in this country." (PMID 29213481, 2016). "One patient with LGI1 antibody encephalitis (PTS 21) initially presented with daily dialeptic seizure with olfactory aura, which completely stopped after receiving IVIG with high-dose steroids." (PMID 26771547, 2016). "In order to improve clinical recognition we report the cases of two Brazilianpatients who presented with characteristic FDBS (illustrated by videos) and anti-LGI1 encephalitis." (PMID 29213481, 2016). "The most representative condition is LGI1-encephalitis, previously known as limbic encephalitis with VGKC complex antibodies." (PMID 23983403, 2013). "The occurrence of anti-LGI1 encephalitis alongside MOG-IgG is a relatively rare phenomenon." (PMID 40703404, 2025). "The co-occurrence of anti-LGI1 encephalitis and MOG-IgG is a rare phenomenon." (PMID 40703404, 2025). "However, the relationship between HHCY and anti-LGI1 encephalitis remains insufficiently understood." (PMID 41473232, 2025). "Therefore, precise localization of these subcortical structural alterations in anti-LGI1 encephalitis holds significant potential as vital biomarkers for elucidating the clinical presentations and neuropsychological consequences of this condition." (PMID 40688080, 2025). "This association may be attributed to the higher prevalence of comorbidities in older individuals, as well as the advanced average age of patients with anti-GABABR encephalitis and anti-LGI1 encephalitis." (PMID 40170898, 2025).
encephalitis (continued). "Postictal MRI changes may also resemble LGI1 encephalitis; therefore, careful clinical correlation is required." (PMID 40271344, 2025). "Finally, in our cohort all patients with anti-LGI1 Ab-mediated encephalitis received at least first-line immunotherapy—a known modulator of long-term disability." (PMID 40281286, 2025). "Other deficits observed after anti-LGI1 ab-mediated encephalitis include mood impairment and fatigue, therefore, our current outcome measures may not have reflected all possible morbidity in this population." (PMID 40281286, 2025). "T2/fluid-attenuated inversion recovery (FLAIR) hyperintensity in the medial temporal lobe is a common manifestation on the conventional MRI and bilateral temporal lobe hypermetabolism on positron emission tomography (PET) in patients with anti-LGI1 encephalitis." (PMID 40688080, 2025). "We report a case of anti-LGI1 antibody encephalitis combined with MOG-IgG." (PMID 40703404, 2025). "We believe that the decision on relapse of anti-LGI1 encephalitis must be carefully made based not only on radiological or serological biomarkers but also on neurological assessment of disease-specific symptoms, such as FBDS or a substantial rise in the CASE score." (PMID 41164023, 2025). "However, the demographic, clinical, and prognostic characteristics of early-onset LGI1-Ab encephalitis have yet to be systematically elucidated." (PMID 41058269, 2025). "We hypothesized that disruptions in directed or effective connectivity within intrinsic brain networks contribute to memory, cognition, and motor impairments in anti-LGI1 encephalitis patients." (PMID 40919049, 2025). "Our findings suggest that anti‐LGI1 encephalitis pathogenesis may involve aberrant metabolic covariance networks underlying cognitive deficits, memory impairment, and psychiatric symptoms." (PMID 41399525, 2025). "The resting-state fMRI scans using group independent component analysis approach demonstrate enhanced functional connectivity within the default mode network, visual network, and sensorimotor network in patients with anti-LGI1 encephalitis compared with controls." (PMID 40688080, 2025). "We report four cases of anti-LGI-1 encephalitis in patients with SLE." (PMID 39965877, 2025). "Neuroimaging techniques have revealed significant functional and structural abnormalities in brain regions that are implicated in emotions, memory, and seizures in patients with anti-LGI1 encephalitis, including the medial temporal lobe, amygdala, hippocampus, cingulate cortex, and insula." (PMID 40919049, 2025). "While initial presentation typically involves FBDS followed by encephalopathy, anti-LGI1 encephalitis is often misdiagnosed as viral encephalitis, psychiatric disorders, and stroke, leading to delayed diagnosis and treatment, and increasing patient morbidity and mortality." (PMID 40519939, 2025). "Therefore, our surface deformation results, in conjunction with previous findings, reinforce the crucial role of the amygdala in seizure occurrence and transmission in anti-LGI1 encephalitis." (PMID 40688080, 2025). "Here, we report a case of anti-LGI1 encephalitis combined with positive MOG-IgG." (PMID 40703404, 2025). "PET‐FDG was compatible with encephalitis, while serum LGI1 antibodies were positive." (PMID 40542608, 2025). "In terms of clinical manifestations memory impairment and seizures were the predominant initial manifestations in patients with anti-LGI1 encephalitis, while FBDS, involuntary movements, and autonomic dysfunction frequently appeared as accompanying or progressive symptoms." (PMID 41473232, 2025). "Patients with anti‐LGI1 encephalitis may exhibit persistent cognitive decline, psychobehavioral abnormalities, and mood disorders, including anxiety and depression, seizures, refractory hyponatremia, and other symptoms." (PMID 41399525, 2025). "Additionally, the acute phase of anti‐LGI1 encephalitis is the first to show characteristic FBDS and hyponatremia." (PMID 41399525, 2025).
encephalitis (continued). "Therefore, this study retrospectively analyzed the clinical data of patients with anti-LGI1 encephalitis who were admitted to the neurology departments of two tertiary hospitals in northern China." (PMID 41473232, 2025). "Our findings of shape deformations in the caudate support its vital role in disorders related to the initiation or suppression of movements, which may explain the motor seizures and FBDS observed in anti-LGI1 encephalitis." (PMID 40688080, 2025). "Additionally, we aim to identify key features of the disease, enhance clinicians’ understanding of anti-LGI1 encephalitis, and provide valuable evidence for accurate diagnosis and the development of therapeutic strategies." (PMID 41473232, 2025). "Although rare, recent reports suggest that LGI1 encephalitis may be triggered following COVID-19 exposure whether through infection or vaccination." (PMID 41311428, 2025). "The CSF profile in anti-LGI1 encephalitis may resemble that of certain viral encephalitides; therefore, careful differentiation from infectious etiologies is required in clinical practice." (PMID 41473232, 2025). "Notably, anti-LGI1 encephalitis patients frequently experience epileptic seizures, often originating in the temporal lobe." (PMID 40919049, 2025). "Clinical data from a subset of patients with LGI1 encephalitis." (PMID 41473232, 2025). "Hyponatremia in anti‐LGI1 encephalitis is often attributed to dysregulated vasopressin secretion and altered function of the hypothalamic supraoptic and paraventricular nuclei, yet we found no direct link between serum sodium levels and hypothalamic metabolism." (PMID 41399525, 2025). "Furthermore, we identified inward deformations on the surface of the caudate, a crucial component of the basal ganglia and motor circuit, in patients with anti-LGI1 encephalitis compared with normal controls." (PMID 40688080, 2025). "In this study, 28.7% (23/80) of patients with anti-LGI1 encephalitis were found to have HHCY." (PMID 41473232, 2025). "These alterations in causal interactions across distinct brain regions provide evidence for pathological neural deficits in anti-LGI1 encephalitis and may serve as potential biomarkers for personalized diagnosis and treatment strategies." (PMID 40919049, 2025). "Therefore, this study aims to characterize the cerebral metabolic patterns and specific subgroups in anti‐LGI1 encephalitis using 18F‐FDG PET imaging, and to investigate their associations with clinical manifestation." (PMID 41399525, 2025). "Notably, during the acute phase of anti‐LGI1 encephalitis, we detected metabolic alterations in the HIP and PFC, specifically within Brodmann areas 9 and 46 (BA9/46), suggestive of structural compromise in these regions." (PMID 41399525, 2025). "Therefore, identifying and developing refined biomarkers that characterize structural and functional brain alterations in anti-LGI1 encephalitis is pivotal for facilitating early diagnosis and guiding effective treatment strategies for this condition." (PMID 40688080, 2025). "We integrated single-cell RNA sequencing (scRNA-seq) with flow cytometry of CSF and blood samples in independent cohorts, analysis of autopsy brains and functional studies (focused on the role of invariant T-cell receptor lymphocytes) in a murine immunization model of CASPR2- and LGI1-encephalitis." (PMID 40094812, 2025). "Notably, it is crucial to underscore that the conclusions derived from this study exclusively pertain to patients with encephalitis caused by antibodies against NMDAR, LGI1, or CASPR2." (PMID 40131535, 2025). "Specifically, FBDS are indicative of anti-LGI1 encephalitis." (PMID 39965877, 2025). "Interestingly, the rate of prostate cancer has been reported as 5.1% in LGI1 antibody encephalitis, which is higher than the unadjusted population prevalence." (PMID 39825737, 2025).
encephalitis (continued). "The observed inward deformations in the hippocampus and thalamus not only correlate with clinical severity but also align with the known pathophysiology of anti-LGI1 encephalitis, where LGI1 antibody-mediated disruption of synaptic transmission preferentially targets these regions." (PMID 40688080, 2025). "The clinical characteristics of patients with anti‐LGI1 encephalitis in acute phase n (%)." (PMID 41399525, 2025). "Notably, FBDS, characterized by abnormal muscle contractions in the unilateral face and extremity (arm or leg), often precedes an anti-LGI1 encephalitis diagnosis." (PMID 40919049, 2025). "The case highlights that the assessment using the CASE score over time may be beneficial to define relapse in a setting with insufficient laboratory evidence of anti-LGI1 encephalitis." (PMID 41164023, 2025). "A total of 312 patients with AE were included: 197 (63.1%) with anti‐NMDAR encephalitis, 71 (22.8%) with anti‐LGI1 encephalitis, 20 (6.4%) with anti‐GABAbR encephalitis, 10 (3.2%) with anti‐CASPR2 encephalitis, 10 (3.2%) with anti‐GAD65 encephalitis, and 4 (1.3%) with anti‐AMPAR2 encephalitis." (PMID 39315845, 2024). "Furthermore, about half of the patients with anti-N-methyl-d-aspartate receptor (NMDAR) encephalitis (50%) and anti-leucine-rich glioma-inactivated 1 (LGI1) encephalitis (62%) had psychiatric manifestations." (PMID 37945763, 2024). "Thus, our study provides a mechanistic framework explaining the neuronal hyperactivity of patients with LGI1 antibody encephalitis." (PMID 39141878, 2024). "Similarly, encephalitis with LGI1 antibodies was confirmed in cats with complex focal seizures and orofacial movements." (PMID 39403212, 2024). "Moreover, because the median age of patients with LGI1-Ab encephalitis is relatively high, the possible development of neurodegenerative disorders must be considered, as observed in 1 patient in this study." (PMID 38603771, 2024). "Anti-LGI1, anti-CASPR2, and anti-GAD65 encephalitis are rarely associated with tumors." (PMID 39539648, 2024). "Classification as probable anti-LGI1 encephalitis relies on the presence of subacute onset (< 3 months) cognitive dysfunction associated with faciobrachial dystonic seizures or frequent (> 5 per day) stereotypical focal seizures (excluded alternative diagnoses)." (PMID 39706227, 2024). "In addition, serum LGI1-Ab titers at the initial episode were determined in 17 relapsing patients and 42 controls with a serum sample available within 3 months from encephalitis diagnosis." (PMID 38603771, 2024). "Anti-LGI1 encephalitis is a rare form of autoimmune encephalitis." (PMID 39867015, 2024). "Moreover, a systematic review tried to clarify distinct metabolic patterns of 18F‐FDG PET/CT among different AE subtypes, mainly focusing on anti‐NMDAR encephalitis and anti‐LGI1 encephalitis." (PMID 38948940, 2024). "Previous studies have reported that 80.8% of patients with anti-LGI1 encephalitis may experience seizures, commonly in middle-aged and elderly males." (PMID 39539648, 2024). "Given that most patients with anti-LGI1 encephalitis become seizure-free after treatment of encephalitis and discontinuation of ASM, these MRI markers may be of modest predictive value for seizure persistence." (PMID 37278857, 2024). "Additionally, we compared the clinical characteristics of anti-NMDAR encephalitis and anti-LGI1 encephalitis in those who developed acute symptomatic seizures." (PMID 39539648, 2024). "There are various types of autoimmune encephalitis; in young adults, particularly women, anti-N-methyl-D-aspartate receptor antibody (anti-NMDAR Ab) encephalitis is common, while in late adulthood, anti–leucine-rich glioma-inactivated 1 (anti-LGI1) encephalitis is the most prevalent." (PMID 39410652, 2024). "Moreover, anti-LGI1 encephalitis had the highest proportion of cognitive impairment, with a significant difference compared to anti-NMDAR encephalitis [71.43% (15/21) vs. 31.82% (7/22), p = 0.009]." (PMID 39539648, 2024).